CETP (cholesteryl ester transfer protein)
Diseases named in the same sentence as CETP in open-access papers (continued):
Sharing a sentence is not in itself a finding about the gene and the disease.
atherosclerosis (continued). "Here, we applied time-restricted feeding (TRF) as a strategy to counteract atherosclerosis development during CD in female APOE∗3-Leiden.CETP mice, a well-established model for humanized lipoprotein metabolism." (PMID 37356205, 2023). "As expected, the expression of CETP increased atherosclerosis in apoE−/− mice (13.1 ± 2.2% compared with 5.9 ± 1.2% for ApoE−/− mice in the presence and absence of CETP expression, respectively; P = 0.005), confirming results from an earlier study." (PMID 37004910, 2023). "The results of randomized controlled trials of CETP inhibitors to increase serum HDL-C for the prevention of ASCVD or progression of atherosclerosis have been disappointing, leading to the discontinuation of most drugs in this class." (PMID 37568484, 2023). "Both tissues of both atherosclerosis models showed CETP mRNA expression in the CETP-positive (CETP+) bone marrow (BM) recipients compared to the CETP-null (CETP0) BM recipients." (PMID 37892238, 2023). "Atherosclerotic lesion area in the aortic arch of apoE−/− mice was 5.9 ± 1.2%; CETP expression significantly increased atherosclerosis in apoE−/− mice (13.1 ± 2.2%)." (PMID 37004910, 2023). "Despite the possible beneficial use of apoC1 as a CETP inhibitor against atherosclerosis, strategies aiming at inducing very high plasma levels of apoC1 would not be relevant because of the possible hypertriglyceridemic effect." (PMID 36471375, 2022). "Human apoC1 prevented extension of aortic atherosclerotic lesions in rabbits fed with cholesterol-rich diet while, on the opposite, CETP activity was found to be correlated positively with the extent of atherosclerosis." (PMID 36471375, 2022). "CETP-Tg and PLTP-Tg mice have significantly low HDL levels and a high risk of developing atherosclerosis." (PMID 35982498, 2022). "Conversely, rodents, which lack CETP, are naturally resistant to the development of atherosclerosis." (PMID 34849601, 2022). "This review focuses on the functions of CETP, the role of CETP in atherosclerosis, the different CETP inhibiting agents developed, and the future of CETP inhibition." (PMID 34849601, 2022). "CETP leads to a net reduction of HDL-C in plasma, which increases the risk of atherosclerosis development." (PMID 35514441, 2022). "Hyperlipidaemic APOE*3Leiden.CETP transgenic mice not only develop spontaneous atherosclerosis but can also be used for induction of lesions in the aortic valve with similarities to changes observed in human CAVS." (PMID 35751904, 2022). "Loss of function genetic mutations in CETP and lower concentrations of CETP are associated with lower LDL-C and increased HDL-C, and lower risk of CVD, which has made CETP a major pharmacological target for CVD and atherosclerosis prevention." (PMID 35694676, 2022). "CETP mouse is widely used in atherosclerosis research and has been very useful in understanding lipid metabolism and drug discovery." (PMID 33570721, 2021). "In doing so, CETP action leads to a net reduction of HDL-cholesterol in plasma, apparently increasing the risk of atherosclerosis development." (PMID 33430172, 2021). "APOE*3-Leiden.CETP mice with modest hyperlipidemia and atherosclerosis can develop atherothrombosis upon transient Proc-silencing." (PMID 34052976, 2021). "Rabbits are known to have abundant plasma cholesteryl ester transfer protein (CETP), which is advantageous for studying CETP and its relationship with atherosclerosis." (PMID 34445123, 2021). "With dietary cholesterol, expressing of CETP promotes cholesterol reverse transport and decreases atherosclerosis in SR-BI null mice, but severely aggravates atherosclerosis in apoE3-leiden mice." (PMID 35082691, 2021).
atherosclerosis (continued). "Due to its activity in promoting the transfer of cholesteryl esters (CE) and triglycerides between pro- and anti-atherogenic lipoproteins, CETP is expected to play a role in the pathophysiology of atherosclerosis." (PMID 33799675, 2021). "In animal models, CETP inhibition protected transgenic mice expressing human CETP as well as rabbits naturally expressing CETP against atherosclerosis." (PMID 34367144, 2021). "In conclusion, rimonabant decreases atherosclerosis development in lean hyperlipidemic E3L.CETP mice, as explained by decreased hepatic VLDL particle production and accelerated turnover of VLDL leading to a reduction in plasma non-HDL-C." (PMID 33766515, 2021). "Release of ICAM-1 from vascular endothelial cells was reduced with PCSK9i alirocumab and anti-PCSK9 vaccine AT04 in the APOE∗3Leiden.CETP transgenic mouse model for hyperlipidemia and atherosclerosis." (PMID 34336112, 2021). "Female APOE*3-Leiden.CETP mice were fed a Western-type diet to induce advanced atherosclerosis, followed by an injection with a small interfering RNA targeting Proc (siProc)." (PMID 34052976, 2021). "CETP KO rabbits had significant less atherosclerosis in both aorta and coronary arteries than WT rabbits." (PMID 33603774, 2021). "Cholesterol-ester transfer protein (CETP) plays a role in atherosclerosis, the inflammatory response to endotoxemia and in experimental and human sepsis." (PMID 34367144, 2021). "We investigated the effect of such lipid-lowering interventions on atherosclerosis in APOE*3-Leiden.CETP mice, a well-established model for hyperlipidemia." (PMID 31843957, 2020). "In this study, we tested alirocumab and/or evinacumab on top of atorvastatin as high-intensive lipid-lowering strategy to evaluate their effect on regression of pre-existent atherosclerosis in APOE*3-Leiden.CETP mice." (PMID 31843957, 2020). "We subjected APOE*3‐Leiden.CETP mice to weekly shifts in light‐dark cycle and observed a striking increase in atherosclerosis development." (PMID 31599473, 2020). "The APOE*3-Leiden.CETP mice are prone to atherosclerosis development and respond well to hypolipidemic drugs." (PMID 31843957, 2020). "In this study, we exposed female APOE*3-Leiden.CETP mice, a well-established model for human-like lipid metabolism and atherosclerosis, to either a regular light-dark cycle or to constant bright light for 14 weeks." (PMID 32915671, 2020). "It should be noted, however, that only female APOE*3‐Leiden.CETP mice develop hypercholesterolemia and atherosclerosis upon feeding a cholesterol‐rich diet." (PMID 31599473, 2020). "The recently developed apoE*3‐Leiden.CETP (E3L.CETP) mouse model of atherosclerosis appears to be the one that most closely replicates the features of human disease." (PMID 32428130, 2020). "Mutations in human CETP are associated with increased HDL cholesterol levels and reduced levels of the atherosclerosis-promoting LDL cholesterol." (PMID 33575564, 2020). "Various medicines, such as HMG-CoA reductase inhibitors (statins), cholesteryl ester transfer protein (CETP) inhibitors (anacetrapib), and cholesterol absorption inhibitors (ezetimibe), have been clinically proven in the treatment of atherosclerosis." (PMID 32565865, 2020). "On the other hand, we found that the activation of thermogenic adipocytes by either cold or CL treatment reduced hypercholesterolemia and protected from the development of atherosclerosis in APOE3L.CETP- mice (E3L.CETP)." (PMID 30813320, 2019). "PCSK9 inhibition decreased total cholesterol in serum of APOE*3Leiden.CETP mice and prevented the development of atherosclerosis." (PMID 31366894, 2019). "CETP, an important regulator of plasma lipoprotein, appeared to be directly related to atherosclerosis in several studies." (PMID 31013851, 2019). "Inhibition of CETP activity reduces aortic lesions and inhibits the progression of atherosclerosis in rabbits." (PMID 30187887, 2018).
atherosclerosis (continued). "Our results reinforce the importance of regular exercise in the prevention and regression of atherosclerosis in an animal model that resembles human lipoprotein metabolism conferred by the presence of CETP." (PMID 29867549, 2018). "Some drugs are prescribed to reduce atherosclerosis, such as torcetrapib (against hypercholesterolemia), anacetrapib (to treat hypercholesterolemia), and evacetrapib (to inhibit CETP)." (PMID 29301350, 2018). "Cinnamon was found to inhibit the atherosclerosis process by the prevention of apoA-1 glycation and inhibition of cholesteryl ester transfer protein (CETP) in hypercholesterolemic zebrafish." (PMID 30423840, 2018). "In conclusion, MOS decreased the progression of atherosclerosis up to 54% in E3L.CETP mice, which was largely explained by a reduction in plasma non‐HDL cholesterol." (PMID 29665623, 2018). "We found that S. cerevisiae‐derived MOS indeed decreased the progression and severity of atherosclerosis in E3L.CETP mice." (PMID 29665623, 2018). "Since the prebiotic inulin is thought to beneficially affect gut microbiota, we aimed to determine the effect of inulin supplementation on atherosclerosis development in APOE*3-Leiden.CETP (E3L.CETP) mice." (PMID 30409998, 2018). "Supplementation with L-carnitine seems to improve some features of CVD although it raises plasma TMAO and TMA levels, and even TMAO showed positive effects against atherosclerosis in ApoE−/− transgenic mice expressing cholesteryl ester transfer protein CETP." (PMID 30275434, 2018). "Because studies looking at the effects of CETP expression on lipid metabolism and atherosclerosis have produced contradictory results, generating a new transgenic pig model will be helpful for further CETP-related research." (PMID 28893253, 2017). "The concept of CETP inhibition is based on the following observations: rodents are naturally CETP deficient, display high HDL-C and are resistant to diet-induced atherosclerosis." (PMID 28342064, 2017). "Our recent study using knock-out rabbits demonstrated that deletion of CETP gene in rabbits protects against cholesterol diet-induced atherosclerosis." (PMID 28767652, 2017). "In our study, high expression of the CETP gene was inborn, and the HCD was used as an arteriosclerotic auxiliary to further explore the roles of the CETP gene in the development of atherosclerosis and plaque formation." (PMID 29317793, 2017). "In the study, we generated transgenic (Tg) rabbits that overexpressed the human CETP gene to examine the influence of CETP on the development of atherosclerosis." (PMID 29317793, 2017). "The results of introducing the CETP gene into rodents, which are naturally CETP-deficient, showed reduced HDL levels and severe atherosclerosis (AS) development." (PMID 28893253, 2017). "Experimental studies on genetically CETP- deficient groups as well as clinical trials involving inhibition of CETP7 have provided conclusive evidence that CETP plays a crucial role in atherosclerosis." (PMID 28733595, 2017). "Recently, we described that activation of thermogenic adipocytes reduces total cholesterol levels and atherosclerosis by accelerating lipoprotein remnant formation and clearance in female E3L.CETP mice." (PMID 28422089, 2017). "Genetic deficiency of CETP in rabbits has beneficial effects on enhancing HDL function and reducing atherosclerosis." (PMID 29317793, 2017). "Advanced data mining also connected CETP to the atherosclerosis pathway, which led us to investigate the role of CETP in MCF-7 cells." (PMID 28050232, 2016). "Till now, Cholesteryl ester transfer protein (CETP) has been envisaged as a feasible molecular target in atherosclerosis, but for the first time, we show that CETP contributes to BC cell survival when challenged with cholesterol depleting agents." (PMID 28050232, 2016).
atherosclerosis (continued). "High plasma concentrations of CETP are associated with low HDL-C which led to the development of CETP inhibitors that raise HDL-C levels and reduce atherosclerosis in experimental animals." (PMID 27293313, 2016). "For this purpose, we employed transgenes for human APOE-Leiden and CETP, both of which had been previously used to promote atherosclerosis development in mice in a dominant manner." (PMID 26694027, 2015). "Early reports that CETP gene transfer increased atherosclerosis in mice, and that CETP inhibition reduced lesions in cholesterol-fed rabbits fuelled enthusiasm for the approach." (PMID 26236237, 2015). "This vaccine induced the generation of anti-CETP antibodies that reduced plasma CETP activity, alleviating the development of both atherosclerosis and NASH in HFC diet-fed rabbits." (PMID 25486007, 2014). "Inhibition of atherosclerosis by atorvastatin in APOE*3Leiden.CETP mice has been observed previously." (PMID 25139399, 2014). "Although HDL-C contributed to some extent, we observed that niacin’s attenuating effect on atherosclerosis development in APOE*3Leiden.CETP mice, fed a Western-type diet with 0.1% cholesterol, is largely explained by its lipid-lowering effect." (PMID 23840481, 2013). "Several mutations in the CETP gene have been identified as a cause of CETP deficiency and change of HDL-C levels, but the associations of these single nucleotide polymorphisms (SNP) and susceptibility to atherosclerosis still lacks consistency." (PMID 24283500, 2013). "In fact, cholesterol exposure generally is a good predictor of atherosclerosis development in E3L.CETP mice (Princen and Rensen, unpublished observations)." (PMID 23717502, 2013). "In another experiment, a vaccine was designed to target both HSP65 and cholesteryl ester transfer protein (CETP) in order to obtain both a positive effect on the immune reactions relevant in atherosclerosis and on blood lipids." (PMID 23635324, 2013). "The relationship between plasma CETP, HDL-C, and atherosclerosis is complex, and CETP gene polymorphisms have been studied to better define this relationship." (PMID 24319689, 2013). "Pharmacological inhibition of CETP alleviated atherosclerosis and other cardiovascular diseases, as well as metabolic syndrome." (PMID 23430930, 2013). "High plasma CETP concentration is associated with reduced HDL-C, a strong and independent risk factor for atherosclerosis." (PMID 24319689, 2013). "The inability of anacetrapib to significantly reduce aortic cholesterol is most likely model dependent, since both torcetrapib and dalcetrapib significantly reduced plague burden in atherosclerosis models that endogenously express CETP." (PMID 23801661, 2013). "We verified the effects of varying activities of plasma CETP on postprandial lipemia and precocious atherosclerosis in asymptomatic adult women." (PMID 21609439, 2011). "The mechanisms that control the cholesteryl ester transfer protein (CETP) have attracted attention, since plasma CETP concentration is associated with increased risk for premature atherosclerosis." (PMID 19558660, 2009). "A typical example would be association between polymorphisms in the apolipoprotein E (APOE), cholesteryl ester transfer protein CETP, stromelysin-1 and β-fibrinogen with progression of atherosclerosis, cardiovascular events and death." (PMID 20040945, 2008). "Accordingly, the humanised dyslipidaemic E3L.CETP mice represent an early vascular ageing phenotype (EVA) and therefore should provide an unique insight into EVA induced by life-long hyperlipidaemia a predisposing factor for early atherosclerosis development." (PMID 40240752, 2025). "Early atherosclerosis lesions were occasionally present only in 40-week-old or older E3L.CETP mice." (PMID 40240752, 2025).
atherosclerosis (continued). "The original hypothesis was that the effect of polymorphisms in the CETP gene on AHRR is mediated by CETP protein activity on lipid profile (mainly by altering HDL-C and TG levels) and thus on atherosclerosis." (PMID 39201274, 2024). "However, both models are very suitable to study inflammation in atherosclerosis development, while the APOE*3-Leiden.CETP model seems most suited to study the lipid-modulating effects of interventions on atherosclerosis development." (PMID 38428154, 2024). "Presl., Lauraceae (C. cassia), another species that is also widely referred to as cinnamon, suppressed atherosclerosis development by preventing apoA-1 glycation and downregulating cholesteryl ester transfer protein (CETP) in hypolipidemic zebrafish both in vivo and in vitro." (PMID 38255895, 2024). "The impact of CETP on atherosclerosis has been investigated for several decades." (PMID 37004910, 2023). "On the other hand, experimental evidence, mainly from genetically modified mice, supports the concept that CETP may protect against atherosclerosis when the LDL receptor function is preserved." (PMID 37892238, 2023). "To determine whether CETP expression in macrophages affects atherosclerosis development, we transplanted bone marrow from transgenic mice expressing simian CETP or non-expressing littermates into hypercholesterolemic LDL-receptor-deficient mice." (PMID 37892238, 2023). "CETP expression and plasma activity may modulate atherosclerosis, and its role is likely highly to be dependent on metabolic context and genetic background." (PMID 37892238, 2023). "Therefore, this study re-evaluated the role of CETP expression in macrophages with a preserved expression of Nnt in the development of experimental atherosclerosis." (PMID 37892238, 2023). "These overall changes in the macrophage immune-metabolic profile reveal new local functions of CETP that might be relevant for atherosclerosis and other inflammatory contexts." (PMID 36139808, 2022). "These localized functions of CETP may be relevant for the prevention of atherosclerosis and other inflammatory diseases." (PMID 36139808, 2022). "CETP may play a role in atherosclerosis development, and we found higher plasma levels of CETP in patients with ISR." (PMID 35265678, 2022). "Rabbits have been a frequently used animal model of hyperlipidemia and atherosclerosis because of the similarity of their lipoprotein metabolism to humans, such as the expression of LDL-rich lipoproteins in plasma, CETP and apolipoprotein B mRNA editing (except for the deficiency of hepatic lipase)." (PMID 36361754, 2022).